INS (insulin)
Diseases named in the same sentence as INS in open-access papers (continued):
Sharing a sentence is not in itself a finding about the gene and the disease.
Insulin resistance (continued). "The primary aim of this study is to determine the efficacy of two different structured dietary interventions on insulin sensitivity, in adolescents with clinical evidence of insulin resistance and/or prediabetes treated with metformin." (PMID 20868506, 2010). "Eight experimental studies, 5 of which were RCTs, examined the effect of exercise interventions on changes in markers of the metabolic syndrome, primarily in the form of fasting insulin and insulin resistance." (PMID 20459784, 2010). "This comprehensive phenotypic dataset allows us to identify two blood lipid factors and segregate insulin resistance factor into its glucose and insulin components, which can have different biological determinants." (PMID 20181263, 2010). "Normal-weight patients with type 2 diabetes showed low plasma insulin concentration, whereas overweight patients with type 2 diabetes showed apparent insulin resistance and high plasma insulin concentration." (PMID 20181219, 2010). "Tissue-specific insulin resistance is thought to further enhance a proinflammatory condition because insulin itself can exert antilipolytic and anti-inflammatory effects." (PMID 20169173, 2010). "Targeting kinases related to insulin signaling and inflammation and/or reducing lipid overspill are potentially effective strategies to treat insulin resistance." (PMID 20721358, 2010). "Activation of the renin-angiotensin-aldosterone system (RAAS) can interfere with insulin signaling as well, promoting and exacerbating insulin resistance in patients with type 2 diabetes." (PMID 21172030, 2010). "ROS themselves can induce insulin resistance or adversely affect the production of insulin by the pancreas." (PMID 20307313, 2010). "Whereas elevated fasting insulin is often considered as a marker of insulin resistance, stimulated insulin concentrations also convey information about the capacity of beta cells to secrete insulin relative to the level of insulin resistance." (PMID 21162746, 2010). "Of these, TNF-α has been shown to alter adipogenesis and to inhibit insulin signalling in mice suggesting that low-grade inflammation induces insulin resistance." (PMID 21179199, 2010). "2-h post glucose insulin level is an effective tool to monitor insulin resistance in PCOS patients and improves significantly after metformin therapy, similar to improvements observed in clinical, hormonal and metabolic parameters." (PMID 21234175, 2010). "This was likely a consequence of FFA-induced insulin resistance as evidenced by the increase in the mean plasma insulin and C-peptide concentration during the 48-hour lipid infusion (p = 0.01 and p = 0.04, respectively)." (PMID 20158910, 2010). "Normal healthy β cells can compensate for insulin resistance by increasing insulin secretion or β-cell mass." (PMID 20100676, 2010). "If additional components, like insulin, are included in the MetS definition, they will direct the unifying concept accordingly, in this case towards insulin resistance." (PMID 20513248, 2010). "On the other hand, insulin level at 120th minute was the best indicator of insulin resistance in the prepubertal girls." (PMID 21274322, 2010). "To date, many lines of evidence seem to show that in humans chronic activation of proinflammatory pathways of insulin targetted cells can result in obesity/steatosis -related insulin resistance." (PMID 20426802, 2010). "So, this study was carried out to investigate the role of H2S in insulin secretion and development of insulin resistance." (PMID 21264117, 2010). "For instance, in Korean population, the validity of HOMA-IR as a surrogate measure of insulin resistance in lean type 2 diabetic subjects with the insulin secretory defect is disputed." (PMID 20529329, 2010).
Insulin resistance (continued). "Increased adipose tissue inflammation will contribute to insulin resistance by disrupting insulin-dependent signaling pathways, leading to increased delivery of free fatty acids to the liver, and thereby contributing to hepatic steatosis." (PMID 19513120, 2009). "Hyperglycaemia in critical illness is believed to reflect inadequate insulin secretion, hepatic and peripheral insulin resistance, and an increase in the counter-regulatory hormones cortisol, catecholamines, glucagon and growth hormone." (PMID 19439067, 2009). "The present data demonstrate that the application of arrayed genome-wide screening technologies to insulin signaling is fruitful and is likely to reveal novel drug targets for insulin resistance and the metabolic syndrome." (PMID 19727444, 2009). "Effect of GC includes impaired insulin-dependent glucose uptake in the periphery and enhanced gluconeogenesis in the liver leading to insulin resistance." (PMID 19997558, 2009). "This latter group of steers had markedly greater blood plasma glucose (0.99 vs. 0.79 g/L) and insulin (2.95 vs. 1.17 μg/L) by day 112, all of which were suggestive of insulin resistance." (PMID 19335898, 2009). "Specifically, adipocytokines appear to have a duality of function, simultaneously mediating inflammation and insulin resistance through their effects on insulin action." (PMID 19368716, 2009). "Thirty percent of subjects were however, subsequently designated as insulin resistant as judged by an increased homeostatic model assessment of insulin resistance value." (PMID 19515259, 2009). "ZDF rats had at 7 weeks comparable blood glucose concentrations but higher plasma insulin (p < 0.01) than control rats, indicating the presence of insulin-resistance." (PMID 19317897, 2009). "As to insulin resistance, PPARα seems to improve—indirectly—insulin sensitivity by increasing hepaticcatabolism of lipids, and thus reducing lipid supply to skeletal muscle." (PMID 19132131, 2009). "Insulin resistance promotes lipolysis, and lipolysis generates toxic lipids, i.e., ceramides, which further impair insulin signaling, mitochondrial function, and cell viability." (PMID 19742171, 2009). "Type 2 diabetes is preceded by insulin resistance or reduced insulin sensitivity, combined with reduced insulin secretion." (PMID 19607676, 2009). "Glucocorticoids are important in the etiology of insulin resistance through down-regulation of insulin signal proteins." (PMID 19646276, 2009). "Testosterone administration can apparently improve insulin sensitivity and reduce insulin levels in the case of physiological supplementation, but it can also lead to increased insulin resistance when attempted in a higher dosage." (PMID 19433001, 2009). "In vivo and in vitro studies of insulin signalling network have provided insights into how insulin resistance can develop in some pathways, whereas insulin sensitivity is maintained in others." (PMID 19828068, 2009). "The disease is characterized by impaired glucose homeostasis, decreased insulin activity and insulin resistance which lead to elevated blood glucose levels." (PMID 19997558, 2009). "We speculate that insulin may be one such factor, since C-peptide levels were significantly lower in female rats (presumably as a consequence of their increased insulin sensitivity) and insulin (and insulin resistance) have been positively linked with AOM carcinogenesis in rats." (PMID 19758446, 2009). "DG is the potential mediator of lipid-induced insulin resistance via activation of novel protein kinase C (nPKC), which inhibits insulin action and is also related to inflammatory response." (PMID 19390588, 2009). "Since insulin injections prevent an accurate measure of endogenous insulin and glucose levels, the 2 OB/D subjects treated with insulin were removed prior to evaluating insulin resistance with the HOMA." (PMID 19936240, 2009).
Insulin resistance (continued). "Changes in glucose, insulin sensitivity and insulin resistance were minimal and comparable between groups." (PMID 19358725, 2009). "The earliest finding of type 2 DM is impairment in the body's response to insulin and this is termed insulin resistance." (PMID 19323780, 2009). "Cameron and Demerath reported high subcutaneous level at the subscapular and the triceps sites to be positively related to both insulin concentration and insulin resistance." (PMID 20003226, 2009). "Insulin signalling pathways were investigated in a 33 year-old woman with immunologic insulin resistance." (PMID 19941665, 2009). "Taken together, these data support the involvement of miR-29a in insulin resistance and the insulin-signaling pathway." (PMID 19689793, 2009). "Adipose tissue has been shown to produce tumor necrosis factor-alpha, which has the ability to reduce insulin secretion and induce insulin resistance." (PMID 19558671, 2009). "Using serum samples collected at 0 and 14 weeks, serum concentrations of glucose, insulin, leptin, ketones and a homeostatic model assessment for insulin resistance (HOMA-IR) were determined." (PMID 19442301, 2009). "Recent understanding that insulin resistance is an inflammatory condition necessitates searching for genes that regulate inflammation in insulin sensitive tissues." (PMID 19787041, 2009). "Adult, or perhaps more aptly, senescent CIH develops rapidly, primarily results from elevated insulin resistance, requires less insulin for glycaemic control and resolves more gradually." (PMID 19245691, 2009). "IFG is determined by an increased hepatic glucose output and by an insulin secretory defect, but IGT is mostly associated with peripheral insulin resistance and it is more strongly associated with the features of metabolic syndrome than IFG." (PMID 19323780, 2009). "Using the HOMA2 model to assess beta cell function and peripheral insulin sensitivity, we have found that pregnant women that presented any degree of glucose intolerance also showed higher degree of insulin resistance at screening." (PMID 19825195, 2009). "Both insulin and thiazolidinediones (TZDs) are effective in the treatment of hyperglycaemia and amelioration of insulin resistance in type 2 diabetes but have side effects including weight gain and fluid retention." (PMID 19298680, 2009). "To challenge the insulin secretion capacity of islets, we placed p38δΔ/Δ and p38δ+/+ mice on a high-fat diet, a widely used model for insulin resistance." (PMID 19135240, 2009). "Several studies have demonstrated that LXR agonists reduce plasma glucose concentrations and increase insulin sensitivity in different models of diabetes and insulin resistance." (PMID 19292929, 2009). "Scenarios (i) and (ii) would be expected to be also closely related to peripheral (muscle) insulin resistance, while scenario (iii) more likely would be related to hepatic insulin resistance." (PMID 19656356, 2009). "Insulin resistance was further demonstrated by elevated resting plasma insulin levels at 4 weeks of diet intervention and at the 45 minute time point of the IPGTT in HFD mice." (PMID 19806198, 2009). "Low leptin levels are present with insulin resistance, and insulin infusion can induce leptin secretion." (PMID 19589139, 2009). "It has often been stated that the disease starts with insulin resistance accompanied by raised insulin and glucose levels." (PMID 19794883, 2009). "Not only PPAR-γ agonists downregulate both the PI3K and the Ras pathway, which are the two main signaling pathways downstream receptors of the IGF system, but also they ameliorate insulin resistance and lower circulating levels of insulin and free IGF-I." (PMID 19609453, 2009). "Accordingly, in mice exposed to a HFD for 6 weeks, treatment with the CB2 agonist JWH-133 enhanced insulin resistance, as assessed by the insulin tolerance test (p<0.05 by two way ANOVA)." (PMID 19513120, 2009).
Insulin resistance (continued). "There were significant associations -and trend- between SRH and levels of inflammatory markers, insulin levels and insulin resistance." (PMID 19788754, 2009). "Considerable evidence indicates that vascular endothelium is a physiological target of insulin and a potential link between insulin resistance and atherosclerosis." (PMID 19695080, 2009). "Type 2 diabetes is characterized by the combination of disturbances in insulin secretion, and an impairment of the effects of insulin, so-called insulin resistance, which is often related to obesity." (PMID 19794883, 2009). "But the observed difference in peripheral insulin resistance (IR) as well as in insulin mediated suppression of hepatic glucose production does not necessarily make IR a better risk predictor than PLG." (PMID 19232132, 2009). "Elevated plasma insulin is widely used as a marker of insulin resistance, at least in large population studies where more accurate methods such as the insulin clamp technique cannot be used." (PMID 19707530, 2009). "We suggest that increased expression of insulin signaling molecules work in concert with increased levels of insulin protecting people in the pre-diabetic state from insulin resistance and metabolic dys-regulation." (PMID 19668377, 2009). "Because of the insulin resistance, the needed dose of insulin in order to achive the hypoglycemia, was 4 times greater than usual." (PMID 19128470, 2009). "Failure for insulin to adequately control blood glucose following a meal is known as 'insulin resistance'." (PMID 19175906, 2009). "At a whole body level, insulin resistance can be defined when higher than normal concentrations of insulin are necessary to maintain euglycemia." (PMID 19781106, 2009). "T2D is a result of several pathophysiological mechanisms, e.g. impaired insulin secretion and insulin resistance in the liver and peripheral tissues." (PMID 19274082, 2009). "Ceramides, for example, attenuate insulin signaling through multiple pathways, and diacylglycerols (DG) are identified as potential mediators of lipid-induced insulin resistance." (PMID 19390588, 2009). "Cells transfected with thegenotype 3a had both increased content of triglycerides and reduced levelsof IRS-1, leading to insulin resistance, as measured by reduced Aktphosphorylation following incubation with insulin." (PMID 19132131, 2009). "Although many genetic and environmental factors contribute to the development of type 2 diabetes, one of the key components is the failure of the pancreatic beta-cell to secrete insulin appropriately in the face of insulin resistance." (PMID 20037650, 2009). "Type 2 diabetes is characterized both by insulin resistance and decreased insulin production, i.a. due to increased β-cell apoptosis." (PMID 19305497, 2009). "Insulin resistance is an alteration in the actionof insulin since besides the normal levels of insulin it cannot trigger the signal for glucose absorption." (PMID 19936118, 2009). "In animal model of type II diabetes mellitus, atorvastatin exerts significant lipid lowering effect, glucose lowering effect and decreased plasma insulin levels and insulin resistance index." (PMID 20442820, 2009). "Increased IL-6 levels in obesity can directly interfere with the insulin signaling and contribute to insulin resistance." (PMID 19545451, 2009). "The elevated fasting plasma insulin levels in the first degree relatives support the notion that they are in the pre-diabetic stage probably on their way to develop overt insulin resistance." (PMID 19668377, 2009). "Moderate alcohol consumption increases HDL, reduces platelet aggregation and fibrinogen levels, increases fibrinolysis, and also improves blood insulin sensitivity and reduces insulin resistance." (PMID 19228434, 2009). "Plasma insulin levels were also higher in HF-fed rats, suggesting the existence of insulin resistance in HF-fed rats." (PMID 19811354, 2009).
Insulin resistance (continued). "This study further showed that high glucose and insulin (which indicate insulin resistance) up-regulate the expression of miR-29a/b in adipocyte cell lines." (PMID 19689793, 2009). "Lean patients are more likely to be older at diagnosis, possess an immune component to their T2DM, and demonstrate certain pathophysiological characteristics, notably less insulin resistance and poorer insulin secretory capacity." (PMID 19732457, 2009). "On the other hand, insulin sensitizers such as thiazolinediones improve cognitive function in mouse models as well as humans with early AD, highlighting the role of insulin resistance in this condition." (PMID 19623253, 2009). "Adiponectin appears to increase insulin sensitivity, with low levels observed in conditions of insulin resistance, such as obesity and type 2 diabetes, and with higher levels being associated with increased insulin sensitivity." (PMID 19589139, 2009). "Because of the insulin resistance, the needed dose of insulin in order to achive the hypoglycemia, was 2 times greater than usual." (PMID 19128470, 2009). "Insulin resistance is defined as the impaired ability of target tissues of fat, liver, and muscle to show various metabolic effects of insulin, including glucose uptake." (PMID 19709445, 2009). "Previous studies suggested other pathways such as the mitogen activated protein kinase (MAPK) pathway and the stress activated protein kinase JNK, which are implicated in insulin induced IRS-1 serine phosphorylation and insulin resistance." (PMID 19169352, 2009). "Palmitate is a precursor of ceramides, which inhibit insulin-stimulated glucose transport and are involved in development of insulin resistance." (PMID 19689798, 2009). "High levels of free fatty acids inhibit insulin-mediated glucose uptake in skeletal muscle leading to insulin resistance." (PMID 19707530, 2009). "Insulin resistance was estimated by HOMA-IR (fasting insulin (mU/l) × fasting glucose (mmol/l)/22.5)." (PMID 19712485, 2009). "Insulin resistance is defined as an impaired responsiveness to both endogenous and exogenous insulin resulting in high blood glucose levels and compensatory hyperinsulinemia." (PMID 18570670, 2008). "In fact, sleep deprivation is an environment important factor in the development of insulin resistance, as well as different types of diets can influence, in terms of improvement or impairment, the insulin sensitivity." (PMID 18986529, 2008). "The triglyceride to high-density lipoprotein cholesterol (TG/HDL-C) concentration ratio has been reported to be as closely related to insulin resistance as is the fasting plasma insulin concentration, a commonly used surrogate estimate of insulin resistance." (PMID 18307789, 2008). "In the presence of significant insulin resistance, insulin effect saturates at high concentrations of insulin, limiting the achievable glycaemic reductions." (PMID 18412978, 2008). "In summary, we have demonstrated that LBW, a known risk factor for development of insulin resistance and type 2 diabetes, is associated with multiple defects in the PI3K/Akt pathway under basal conditions and following in vivo insulin-stimulation." (PMID 19011679, 2008). "Insulin resistance was initiallyrecognized as an “allergy” to insulin, with the production of antibodiesanti-insulin." (PMID 18604303, 2008). "We studied the correlations between fasting and post-lunch serum IGF-I concentrations, and insulin resistance and insulin sensitivity in subjects with various degrees of glucose tolerance." (PMID 19902049, 2008). "Recent studies suggest that the pathophysiology of insulin resistance is closely related to interferences with insulin-mediated intracellular signaling on skeletal muscle cells, hepatocytes, and adipocytes." (PMID 18604303, 2008).